CD4 (CD4 molecule)
Diseases named in the same sentence as CD4 in open-access papers (continued):
Sharing a sentence is not in itself a finding about the gene and the disease.
tumor (continued). "Furthermore, cryo-thermal-activated eosinophils exerted versatile immunologic regulation from innate immunity to anti-tumour adaptive immunity, such as M1 macrophage polarization, DCs maturation, differentiation of CD4-CTL subtypes and enhanced cytotoxicity of CD8+ T cells." (PMID 31519961, 2019). "Thus, cognate interaction between tumor antigen specific CD4+ Th1 cells and TAMs might promote recreation of an immuno-stimulatory tumor micro milieu, thereby facilitating efficient anti-tumoral immune attack." (PMID 30853959, 2019). "Furthermore, the phenotypically matured splenic DCs following cryo-thermal therapy could moderately promote tumor-bearing CD4+ T-cell differentiation into Th1, CD4-CTL, and Th2 sub-lineages." (PMID 30833570, 2019). "IL-4 produced by CD4+ T cells may inhibit angiogenesis, promote the infiltration of eosinophils and macrophages into tumour and exert anti-tumour effects, while IL-5 mainly has immunosuppressive and tumour-promoting function." (PMID 31519961, 2019). "Furthermore, an enhanced antitumor immunological response contributed to preventing tumor recurrence, i.e., Rh2, when used as an adjuvant, was found to trigger CD4+/CD8a+ T-lymphocyte infiltration in tumor tissues and to increase T-lymphocyte cytotoxicity with cancer chemotherapeutic drugs." (PMID 31277214, 2019). "Notably, several CD4+ or CD8+ clones in the blood were also present in the tumor microenvironment." (PMID 31275310, 2019). "Importantly, WT1332-specific CD4+ T cells could not only aid the expansion of WT1-specific CD8+ CTLs but also directly kill HLA class II-positive WT1-expressing tumor cells." (PMID 30430205, 2019). "Conversely, many other subtypes of immune cells including regulatory T cells (Tregs), CD4+ helper T cells, suppressive dendritic cells, and myeloid-derived suppressor cells (MDSCs) traffic to the bone-tumor microenvironment and are more prone to promote tumor progression and metastasis." (PMID 30823602, 2019). "Furthermore, TNFα and IFNγ in combination induce tumor cell senesce mediated by CD4+ T cells (Th1)." (PMID 30833945, 2019). "In addition, in muscle-invasive bladder cancer (MIBC), CD19+ TIB was identified as an independent prognostic factor and serve as antigen-presenting cells (APCs) to activate CD4+ T cell in the tumor microenvironment; the OS of the high CD19+ TIB MIBC patient was significantly longer." (PMID 31662750, 2019). "Moreover, accumulating evidence indicates that one efficacious mechanism by which TGFβ promotes tumour progression and metastasis is regulating CD4+ T-cell-mediated immunity by inducing the differentiation of CD4+ T cells into various subpopulations of T cells." (PMID 31409774, 2019). "Therefore, utilizing a CD8-independent TCR gene rather than TCRs that are functional only in CD8+ T cells offers the potential for significantly higher clinical benefit by the direct anti-tumor effects of CD4+ T cells, and the collaborative anti-tumor effects by CD4+ and CD8+ T cells." (PMID 30626427, 2019). "Therefore, our aim consisted of evaluating the predictive roles of pre-SABR CD8+ T-cell counts, CD8+CD28+ T-cell counts, CD8+CD28− T-cell counts, CD4+ T-cell counts, and Treg-cell counts in peripheral blood for early tumor response to SABR in patients with lung metastases from NSCLC." (PMID 30971280, 2019). "This relatively high CD4+ T cell infiltration might also be responsible for the moderate effects regarding the immune checkpoint inhibitors observed for JA-2042, and displayed a significant tumor reduction by a combination antibody treatment." (PMID 30791466, 2019). "Additionally, due to the lack of IFN-γ inducible expression of class II transactivator (cIITA), MHC class II molecule expression is absent in SCLC cells and significantly lower in SCLC TILs compared with in NSCLC, resulting in reduced presentation of tumor neoantigens to CD4+ T cells." (PMID 31253167, 2019).
tumor (continued). "In addition, regulatory T cells are decreased after adjuvant chemotherapy, which may profoundly drive the development of tumor-specific CD4+ T effector cells." (PMID 31762828, 2019). "In fact, CD4+ T cell memory could be induced by tri-specific antibody treatment targeting immune checkpoint inhibitors to the tumor and activating tumor-specific both CD4+ and CD8+ T cells simultaneously, with the greatest effect observed in the CD4+ TEM and TCM compartments in mice." (PMID 31379821, 2019). "However, at the intermediate (day 33) and late (day 37) timepoints, we observed more than a 13-fold increase in the percentage of CD8+ T cells and a greater than 2-fold increase in CD4+ T cells infiltrating CPR treated tumors compared to tumor size-matched control mice." (PMID 31409394, 2019). "Also, the CD4/Treg ratio correlated with early tumor response to SABR with a clear trend." (PMID 30971280, 2019). "Hence, CD4+ T cell recognition of tumor antigen occurs in an indirect manner." (PMID 30083157, 2018). "Thus, tumors may enforce a dominant inhibition of the anti-tumor CD4 response in the TdLN by recapitulating peripheral self-tolerance mechanisms." (PMID 29844317, 2018). "However, conditional deletion of one Eomes allele in T cells did not alter the number or phenotypes of CD4+ T cells in E.G7 tumor model." (PMID 30619337, 2018). "Therefore, multi-epitopic antigenic cargos linked to CPP stimulating both CD4 and CD8 T cells might also be important to generate a fully functional anti-tumor immune response." (PMID 29508006, 2018). "To explore the immunological mechanisms underlying the enhanced tumor-specific immune response, we assessed the effects of combination therapy on the proportions of MDSCs (CD11b+Gr1+), M2 macrophages (CD11b+F4/80+CD206+ cells), and Tregs (CD4+CD25+FoxP3+ cells) in splenocytes." (PMID 29967612, 2018). "Furthermore, when activated human dendritic cells or macrophages were co-cultured with CD47 positive human tumor cells, SIRPα - Fc-CD40L was shown to enhance phagocytosis of human tumor cells, and in vivo in mice, induced rapid activation of CD4+ and CD8+ dendritic cells." (PMID 30400822, 2018). "In this context, whole tumor cell lysates are excellent sources for the delivery of a wide range of TAAs that will generate MHC class I/II T cell epitopes for inducing the activation of CD4+ T helper and CD8+ cytotoxic T cells simultaneously, and therefore, a more integral immune response." (PMID 29600445, 2018). "Moreover, it is also possible that indirect, macrophage-mediated responses may contribute to the cytotoxicity against MHC class II positive tumors as an adjunct to direct cytotoxic effects of CD4+ T cells on such tumor cells." (PMID 30083157, 2018). "Thus, our results show that the IL-33/ST2 interaction is required for SCC progression and that it is involved in a mechanism that contributes to the recruitment of CD4+ T lymphocytes, dendritic cells, and macrophages, predominantly the M2 phenotype, to the tumor microenvironment." (PMID 30112116, 2018). "A role for the CD4+ T-cell subset in optimizing the antitumor immune response was supported by in vivo studies demonstrating that depletion of CD4+ T lymphocytes promotes tumor progression, whereas their adoptive transfer was correlated with improved tumor regression." (PMID 29403496, 2018). "Thus far, few reports have been published on the association between IDH gene mutations and tumor immune cell infiltration, such as CD8+ T cells, macrophages, and CD4+ T, B, and dendritic cells, as well as the connections between mutations and immune-checkpoint molecules." (PMID 29643764, 2018). "Furthermore, DJ‐1 deficiency decreased the CD4+:CD8+ T‐cell ratio and promoted the development of regulatory T cells 21 that is associated with a positive outcome in CRC 22, suggesting that DJ‐1 promotes tumor progression by inhibiting tumor immunology in CRC." (PMID 29441725, 2018).
tumor (continued). "However, it may be more important that the PD-L1 expressed by the tumor cells suppresses the function of PD-1-expressing normal CD4+ T-cells, resulting in immune evasion." (PMID 29915722, 2018). "Moreover, our recent studies demonstrate that netrin-1/neogenin interactions augment CD4+ T cell chemokinesis and elicit pro-inflammatory responses, suggesting that netrin-1 plays a key role in modulating the function of a tumor and its surrounding cells in the tumor microenvironment." (PMID 30532711, 2018). "Blocking of the EGFR with cetuximab when tumor cells were stimulated with the type 1 cytokine IFNγ and TNFα resulted in the amplification of the production of the T-cell attracting chemokines and resulted in an increased migration of CD4+ and CD8+ lymphocytes in chemotaxis assays in vitro." (PMID 30192802, 2018). "Additionally, the CD4+ T cells expressing the B7H6-specific CAR/T-bet (∆TBOX) may be aiding in eliminating the tumor through cytotoxicity mechanisms, such as FAS-FASL interactions, which RMA cell lines are susceptible." (PMID 29515240, 2018). "Tumors of USP18 deficient mice also displayed an increased CD4+ T-cell infiltration, an increased level of cxcL-10 and hypersensitivity to IFN-λ enhanced up-regulation of CxcL-10 expression, which created a Th1/M1-polarized cytokine tumor environment and inhibited tumor progression." (PMID 29416786, 2018). "Neither tumor CD4 content nor FOXP3 content was associated with DDFS." (PMID 29482642, 2018). "Interestingly, combination treatment increases tumor infiltrating CD4+T, CD8+T and NK+-cells." (PMID 29844873, 2018). "However, histopathological response to NAC is a positive predictor of survival and, although a cause-and-effect relationship cannot be established, the data suggests that increased proportions of committed CD4+ T cells in the tumour regional lymph nodes after NAC translates into a better outcome." (PMID 30075815, 2018). "Interestingly, in healthy individuals NY-ESO-1 specific CD4+ T-cell precursors were found to be actively suppressed by regulatory T cells, suggesting that the cytokine milieu of the tumor microenvironment can dictate and impede natural NY-ESO-1 antitumor immune responses." (PMID 29770138, 2018). "In addition, A. muciniphila can also increase the patient’s response to drugs by increasing the recruitment of CCR9+ CXCR3+ CD4+ T lymphocytes during the immunotherapy of tumor patients with PD-1/PD-L1 and increase the progression-free survival (PFS) of patients after treatment." (PMID 30687277, 2018). "Kreiter and co-workers recently reported a list of mutation-derived, CT26-specific CD4+ and CD8+ T cell “neoepitopes” and showed that immunization with RNA vaccines encoding such neoepitopes elicited robust protection in BALB/c mice challenged with CT26 tumor cells." (PMID 30416985, 2018). "In one of the first studies showing that CD4 T cells have significant antitumor effects, Greenberg and colleagues performed an adoptive transfer of T cells obtained from syngeneic mice vaccinated with irradiated tumor cells that facilitated eradication of disseminated leukemia in recipients." (PMID 29032503, 2018). "The tumor-induced anergic mouse gene signature was significantly enriched in chCD4+ T cells from cancer patients (p = 0.0023) but not from healthy donors (p = 0.275), suggesting that CD4+ T cells may also become anergic in tumor bearing patients including NSLC patients." (PMID 29844317, 2018). "Anti-CTLA-4 antibody primarily effects CD4+ T cells at the priming phase of the immune response, while anti-PD-1/PD-L1 acts predominantly on exhausted T cells within the tumour, which might be essential for overcoming the more immunosuppressive microenvironment in late-stage solid tumours." (PMID 30410056, 2018).
tumor (continued). "Methylation levels at the FOXP3 locus was increased in LN CD4+ T cells from patient with muscle invasive pT2 compared to both non-muscle invasive pTa-Tis staged patients and to the cells from patients with perivesical infiltrating tumours (pT3) (p < 0.05 for both)." (PMID 30075815, 2018). "Thus, the expression of NF-κB in myeloid cells from these two sites might be related to different polarizations of T CD4+ cells with different roles in the development of anti-tumor adaptive immunity." (PMID 29315242, 2018). "Although CD4+ T cells and MHC class II molecules are associated with the tumor antigen-specific immune response, the tumor antigens have been shown to present predominantly in association with MHC class I molecules, and to be recognized by tumor-specific CD8+ T cells." (PMID 30445793, 2018). "Indeed, anti-tumour activity was consistently reduced when TILs were co-cultured with autologous tumour cells in the presence of an anti-MHC class II antibody affirming that CD4+ TILs contribute to functional activity." (PMID 30039427, 2018). "Therefore, the survival observed in MAP17-positive patients may be a complex factor depending on the production of ROS and also related to the CD4/CD8 ratio of cells in the tumor microenvironment." (PMID 29228712, 2017). "Depletion of CD4 T cells with locally secreted IL-12 in late-stage progressive B16 models, where Th2/Tr-type response dominate, eliminates Th2 cells and results in a Th1-dominant cytokine profile in tumor draining lymph nodes and leads to a retarded tumor growth in syngeneic mice." (PMID 28060744, 2017). "Release of tumour neo-antigens and epitope spreading following OV-induced necrosis and pyroptosis of cancer cells leads to the recruitment of scavenging macrophages and Batf3+ dendritic cells, enhanced antigen presentation and subsequent activation of antigen-specific CD4+ and CD8+ T-cells." (PMID 29157300, 2017). "Moreover, a subset of CD4+ T lymphocytes may sustain the primary infection of B lymphocytes or even induce the expansion of tumor B cells mainly through IL-4 and IL-13 release and CD40 engagement, as demonstrated in vitro and in vivo in hu/SCID mouse models." (PMID 28289418, 2017). "Also, CD4+ T cells in tumors have cellular plasticity with both anti- and pro-tumor roles." (PMID 28794686, 2017). "Thus, appropriate interventions to inhibit CD4+CD25+FOXP3+ Treg elevation could aid in preventing tumour progression, and regular monitoring of Treg cells in clinical patients may help to establish their prognosis." (PMID 28253320, 2017). "Treg, therefore, represent a barrier to effective natural anti-tumour immunity, but whether intra-tumoural Treg are recruited from existing peripheral populations or are induced to differentiate from naive CD4 T cells within the tumour microenvironment remains unclear." (PMID 28239749, 2017). "CD4+Teff and Treg clones expressing identical TCRs likely recognize the same antigens, but their activation may have a different effect on the growth of the tumor." (PMID 28638937, 2017). "Thus CD4-AsiCs provide a valuable tool to interrogate the role of individual gene products in CD4 cells in immune protection and pathology in general and in tumor immunity in particular that could potentially be developed for therapeutic use." (PMID 28290464, 2017). "Therefore, therapy with 7 and γδ T cells could be further combined with checkpoint blockade with anti-PD-1/anti-PD-L1 and/or anti-CTLA-4 antibodies to activate anti-tumor CD4 and CD8 αβ T cells that are already present." (PMID 28729550, 2017). "Furthermore, these neoepitope-specific CD4+ T cells could directly induce cancer cell death and tumor regression by altering the tumor-promoting functions of cells in the surrounding tumor microenvironment." (PMID 28488173, 2017).
tumor (continued). "The exact role for type I IFNs in mediating PD-L1 immune escape remains to be elucidated, but it is tempting to speculate that early production of IFN-α by APCs augments IFN-γ production by CD4+ T lymphocytes and NK cells, and thus leads to PD-L1 up regulation in the tumor microenvironment." (PMID 29050360, 2017). "This could be a compensatory response to the increase in the conventional and CD8+ T-cell populations, as the tumours of the treated animals with the highest numbers of CD4+FoxP3+ cells also exhibited the highest numbers of the conventional CD4+FoxP3− T cells and CD8+ cells." (PMID 28194010, 2017). "The second IL-10 peak observed at day 7 in CD4+ cells prompted us to study IL-10 production by other cell populations at this time point, using tumor-free mice, since equivalent results had been observed in lymphoid organs from tumor-free and tumor-bearing mice." (PMID 27926522, 2017). "The Rosenberg group demonstrated dramatic tumor regression in a metastatic cholangiocarcinoma patient treated with a personalized adoptive cell transfer, where over 95% of autologous T cells consisted of CD4+ T cells that recognized a single HLA class-II-restricted neoantigen." (PMID 29234329, 2017). "In this study we showed that inhibiting naive CD4+ T cell recruitment by knocking down PITPNM3 in tumor-bearing humanized mice could reduce TI Tregs, restore immune killing of tumors and suppress tumor growth and metastases, confirming the role of PITNM3 recognition of CCL18 in TI Treg biogenesis." (PMID 28290464, 2017). "Also, CD4+ T cells in tumors have plasticity and have both anti- and pro-tumor roles." (PMID 28794686, 2017). "Therefore, we examined if some of the increased CD4+ T‐cells among the TME and tumor‐free bone of mice with subcutaneous tumors might be CD4+, CD25+, FoxP3+ T‐regs." (PMID 28250928, 2017). "However, a few studies have addressed tumor-specific CD4+ T cells." (PMID 29250133, 2017). "However, it is possible that PD1+ CD4+ T cells may compete for anti PD-1 mAb binding to CD8+ or tumor cells, respectively." (PMID 29070883, 2017). "Moreover, a population of CD4+/CD25-/FOXP3+ T cells was identified at the tumor site of human B-NHLs, suggesting that chronic stimulation of T cells might alter T cell differentiation and FOXP3 expression, independently of CD25." (PMID 29340116, 2017). "As CD4+ cells consist of various subpopulations, each of them could affect tumor behavior." (PMID 28549420, 2017). "By the way, the infusion of bulk cultures containing up to 98% of CD4+ T cells of undefined specificity was carried out in patients without adverse events, thus indicating that such B cell-specific T cells, if present, likely target an antigen(s) overexpressed by tumor cells." (PMID 28289418, 2017). "Furthermore, HDAC inhibition decreases Foxp3 expression in CD4+ T cells, which may increase an anti-tumor immune response by down-regulating suppressive Treg activity." (PMID 29371976, 2017). "The cellular antitumor immune response could effectively eliminate tumor cells and mainly involves the capture and processing of tumor-derived antigens by dendritic cells, the recognition of CD4+ and the cytotoxicity of CD8+ T cells, all of which play central roles in the fight against tumors." (PMID 29283407, 2017). "Furthermore, tumor-specific CD4+ T cells maintained TCR diversity." (PMID 28854279, 2017). "Moreover, the percentages of tumor-infiltrating CD4 + CD25 + Foxp3 + Treg cells were also higher in the treated group than in the controls, with significant increases in the percentages of these Treg cells on days 16 (12.50 ± 1.07 and 8.38 ± 0.17%) and 24 (6.95 ± 1.17 and 2.17 ± 0.74%) (p < 0.01)." (PMID 27703219, 2016). "However intracellular cytokine staining of splenic CD4+ T cells from mice in which tumor escape had occurred indicated an increased rather than decreased proportion of IL-2+ T cells in the presence of tumor-specific B cells, with the majority of T cells co-expressing TNF." (PMID 27121060, 2016).